PIGB (phosphatidylinositol glycan anchor biosynthesis class B)
Description:
Alpha-1,2-mannosyltransferase that catalyzes the transfer of the third mannose, via an alpha-1,2 bond, from a dolichol-phosphate-mannose (Dol-P-Man) to a 2-acyl-6-[alpha-D-mannosyl-(1->6)-2-phosphoethanolamine-alpha-D-mannosyl-(1->4)-alpha-D-glucosaminyl]-1-(1-radyl,2-acyl-sn-glycero-3-phospho)-1D-myo-inositol intermediate to generate a 2-acyl-6-[alpha-D-mannosyl-(1->2)-alpha-D-mannosyl-(1->6)-2-phosphoethanolamine-alpha-D-mannosyl-(1->4)-alpha-D-glucosaminyl]-1-(1-radyl,2-acyl-sn-glycero-3-phospho)-1D-myo-inositol (also termed H6) and participates in the nineth step of the glycosylphosphatidylinositol-anchor biosynthesis (Probable). May also add the third mannose to a 2-acyl-6-[alpha-D-mannosyl-(1->6)-alpha-D-mannosyl-(1->4)-alpha-D-glucosaminyl]-1-(1-radyl,2-acyl-sn-glycero-3-phospho)-1D-myo-inositol (also termed H3) intermediate generating a 2-acyl-6-(alpha-D-mannosyl- (1->2)-alpha-D-mannosyl-(1->6)-alpha-D-mannosyl-(1->4)-alpha-D-glucosaminyl)-1-(1-radyl,2-acyl-sn-glycero-3-phospho)-1D-myo-inositol (also termed H4) (Probable).
Synonyms: GPI-MT-III; PIG-B; DEE80; EIEE80
Tractability: Antibody: UniProt predicts a signal peptide or a membrane-spanning region.
Safety:
Unwanted effects reported when the protein is acted on. In parentheses: how it was acted on, where the effect was seen, and who reports it.
leukopenia or neutropenia (source: ClinPGx)
neutropenia or leukopenia (source: ClinPGx)
Gene: Protein-coding gene on chromosome 15 (55,318,960 to 55,355,648, forward strand). Ensembl gene ENSG00000069943.
Subcellular location: Endoplasmic reticulum membrane
Subcellular location (Human Protein Atlas): Cytosol; Plasma membrane
Pathways (Reactome):
Metabolism of proteins: Synthesis of glycosylphosphatidylinositol (GPI)
Gene Ontology:
Molecular function: dol-P-Man:Man(2)GlcN-acyl-PI alpha-1,2-mannosyltransferase activity; alpha-1,2-mannosyltransferase activity; GPI mannosyltransferase activity; glycosyltransferase activity
Biological process: GPI anchor biosynthetic process
Cellular component: endoplasmic reticulum membrane; membrane
Genetic constraint (gnomAD): Loss-of-function variants: 14 observed, 19.93 expected, observed/expected ratio (o/e) 0.7, 90% interval 0.46 to 1.1. The upper end of that interval is the gene's LOEUF score, 1.1, which puts it in group 4 of 6, group 1 being the genes least tolerant of losing a copy. Missense variants: 260 observed, 260.5 expected, observed/expected ratio (o/e) 1, 90% interval 0.9 to 1.11. Synonymous variants: 90 observed, 96.6 expected, observed/expected ratio (o/e) 0.93, 90% interval 0.79 to 1.11.
Gene-disease validity (ClinGen):
ClinGen rates the evidence that PIGB causes each of these diseases.
developmental and epileptic encephalopathy, 80 (autosomal recessive): Moderate.
Homologues: Orthologues: chimpanzee PIGB (99% identical), macaque PIGB (94% identical), dog PIGB (84% identical), rabbit PIGB (84% identical), pig PIGB (80% identical), rat Pigb (79% identical), mouse Pigb (77% identical), guinea pig PIGB (66% identical), tropical clawed frog pigb (63% identical), zebrafish pigb (52% identical), Drosophila melanogaster PIG-B (38% identical), Caenorhabditis elegans pigb-1 (29% identical). Paralogues in human: ALG12 (20% identical), ALG9 (19% identical).
Diseases named in the same sentence as PIGB in open-access papers:
PIGB is named in the same sentence as 11 diseases in open-access papers, as found by Europe PMC text mining. Sharing a sentence is not in itself a finding about the gene and the disease. The quoted sentences say what the papers report.
axonal neuropathy (1 paper, 2020). Any nerve disorder affecting the axon of a nerve. "Ten mutations of the human PIGB gene were recently reported to cause inherited GPI deficiencies characterized by axonal neuropathy and metabolic abnormalities." (PMID 32051283, 2020).
DOORS syndrome (1 paper, 2025). DOORS syndrome (also known as DOOR syndrome) is a multiple congenital anomalies-intellectual disability syndrome characterized by sensorineural hearing loss (deafness), onychodystrophy, osteodystrophy, mild to profound intellectual disability, and seizures. "Additionally, any PIGB variants are accompanied by a reduction of inhibitory GABAergic interneurons, In severe phenotype of epilepsy due to PIGB variants, DOORS syndrome may be observed." (PMID 40230662, 2025).
epilepsy (1 paper, 2025). A brain disorder characterized by episodes of abnormally increased neuronal discharge resulting in transient episodes of sensory or motor neurological dysfunction, or psychic dysfunction. "These variants provide critical insights into epilepsy pathophysiology, with the PIGB variant notably linked to elevated ALP levels, suggesting a potential biomarker for further investigation." (PMID 40230662, 2025). "This study underscores the value of WES in uncovering genetic variants associated with epilepsy, focusing on two novel findings: AP3B2 (NM_001278512.2: c.3190G > A; p.Val1064Ile) and PIGB (NM_004855.5: c.1664G > C; p.Ter555Serext∗54)." (PMID 40230662, 2025). "This study highlights the value of WES in identifying genetic variants associated with epilepsy, particularly the novel AP3B2 and PIGB variants." (PMID 40230662, 2025). "The influence of PIGB gene defects in epilepsy development is well understood." (PMID 40230662, 2025).
laminopathies (1 paper, 2024). "The fact that the phenotype is observed only in muscle upon PIGB deficiency may be related to the fact that even in laminopathies caused by lamin mutations, the tissues in which the pathology manifests itself differ depending on the type of mutation." (PMID 38261271, 2024). "Investigating the molecules involved, including PIGB, in the establishment of a consistent lamin network would greatly contribute to nuclear biology and increase understanding of the pathogenesis of laminopathies." (PMID 38261271, 2024).
Seizure (1 paper, 2023). A seizure is an intermittent abnormality of nervous system physiology characterized by a transient occurrence of signs and/or symptoms due to abnormal excessive or synchronous neuronal activity in the brain. "However, PIGB, which is implicated in hereditary epileptic seizures, is among the top 10 genes driving the separation of cluster B4 (FDR P = 0.003, log2(FC) = 1.02).37,38 Notably, PIGB was also significantly altered in cluster C2 (FDR P = 0.048, log2(FC) = −0.783)." (PMID 37881482, 2023).
cancer (1 paper, 2014). A tumor composed of atypical neoplastic, often pleomorphic cells that invade other tissues. "Our findings indicate that PIGB is involved in sensitizing cancer cells to both gemcitabine and AraC, suggesting a possible role in oncogenic pathways as well as chemoresistance." (PMID 24483146, 2014).
PIGB also shares sentences with these, for which no sentence is quoted: acute myeloid leukemia (1 paper); demyelinating polyneuropathies (1); GPI deficiencies (1); infection (1); neuropathy (1).